PDPN (podoplanin)
Diseases named in the same sentence as PDPN in open-access papers (continued):
Sharing a sentence is not in itself a finding about the gene and the disease.
lung adenocarcinoma (36 papers, 2007 to 2025). A carcinoma that arises from the lung and is characterized by the presence of malignant glandular epithelial cells. "Clinical cases characterized by the presence of podoplanin-expressing CAFs display a poor response to EGFR tyrosine kinase inhibitors (EGFR-TKIs) in patients with lung adenocarcinoma harboring constitutively active mutations of EGFR." (PMID 32546182, 2020). "Again, these results are in agreement with clinical reports showing that podoplanin expression in CAFs is associated with a poor prognosis in patients with lung adenocarcinoma." (PMID 30736372, 2019). "While PDPN expression on cancer-associated fibroblasts (CAFs) of human lung adenocarcinomas is associated with poor prognosis, increased PDPN expression in human colorectal CAFs was a significant indicator of good prognosis." (PMID 31335913, 2019). "PDPN is also found in some stromal fibroblasts, and an abundance of PDPN-positive stromal fibroblasts is associated with poor prognosis in lung adenocarcinoma, invasive breast cancer, and esophageal squamous cell carcinoma patients." (PMID 28702871, 2018). "Podoplanin is expressed by cancer associated fibroblasts (CAFs) and has been shown to be correlated with a poor prognosis in lung adenocarcinomas." (PMID 20178649, 2010). "Podoplanin (PDPN), a 38-kDa type I transmembrane glycoprotein which is found in some fibroblasts, and an abundance of PDPN-positive fibroblasts is associated with poor prognosis in lung adenocarcinoma, invasive breast cancer, and esophageal squamous cell carcinoma patients." (PMID 31013287, 2019). "In agreement with our findings, the activation of RhoA/ROCK signaling has been identified as a central mechanism by which PDPN + CAFs promote tumor formation in lung adenocarcinoma." (PMID 40842027, 2025). "Co-injection of PDPN-positive vascular adventitial fibroblasts with lung adenocarcinoma cells results in increased tumor formation and metastasis." (PMID 40741180, 2024). "In lung adenocarcinoma patients, PDPN-positive CAFs have been shown to induce resistance to gefitinib, an epidermal growth factor receptor/tyrosine kinase inhibitor (EGFR-TKI) used to treat advanced NSCLC." (PMID 39403603, 2024). "There was an enhanced drug‐resistant effect of lung adenocarcinoma cells observed in PDPN‐positive CAFs." (PMID 36156321, 2023). "In lung adenocarcinoma, podoplanin expression in CAFs predicts poor prognosis, and podoplanin-expressing CAFs promote cancer cell invasiveness via RhoA activation in lung adenocarcinoma." (PMID 37993428, 2023). "The subcutaneous co-injection of human lung adenocarcinoma A549 cells with PDPN-positive vascular adventitial fibroblasts resulted in a high rate of tumor formation, lymph node metastasis, and lung metastasis compared with PDPN-negative fibroblasts." (PMID 35159384, 2022). "PDPN‐positive CAFs can be commonly found in clinical samples of lung adenocarcinoma and are also related to poor survival." (PMID 35603909, 2022). "Podoplanin-positive CAFs drive tumor progression in a xenograft model, and podoplanin expression in CAFs predicts a poor outcome in patients with lung adenocarcinoma." (PMID 32546182, 2020). "Recently, we reported that podoplanin-positive CAFs induce primary resistance to EGFR-TKIs in lung adenocarcinomas exhibiting EGFR mutations, with podoplanin playing a functional role in this effect." (PMID 28429795, 2017). "So far, the effects of podoplanin present on the surface of CAFs on the biological properties of cancer cells have been studied in the case of human lung adenocarcinoma and invasive ductal carcinoma of the pancreas." (PMID 28938000, 2017). "In our previous reports, CAFs-PDPN increased the subcutaneous tumor formation ratio of the lung adenocarcinoma cell line A549 when evaluated using SCID mice." (PMID 25909164, 2015).
lung adenocarcinoma (continued). "In contrast to the SCLC cell lines, CAFs-PDPN increased the number of cancer cells belonging to the lung adenocarcinoma cell line PC9, compared with the number after co-culturing with CAFs-Ctrl (132.3%, P < 0.01)." (PMID 25909164, 2015). "Vascular adventitial fibroblasts in lung adenocarcinoma have biological functions similar to those of CAFs, and PDPN is highly expressed in vascular adventitial fibroblasts in association with cancer progression." (PMID 24354864, 2013). "Targeting the PDPN/MET signaling axis may be a potential therapeutic strategy to overcome resistance to EGFR-TKIs in lung adenocarcinoma patients." (PMID 39403603, 2024). "Interestingly, PDPN is also overexpressed in several kinds of tumors, including lung adenocarcinoma, small lung cell carcinoma, breast carcinoma, and perihilar cholangiocarcinoma." (PMID 40741180, 2024). "Also, increased ezrin in the presence of PDPN‐positive CAFs facilitated aggressiveness in lung adenocarcinoma." (PMID 36156321, 2023). "It was shown using nude mice model, that human vascular adventitial fibroblasts (hVAF) with high PDPN expression enhanced tumor progression of human lung adenocarcinoma cells more than human lung tissue-derived fibroblasts (hLF) with low expression of this glycoprotein." (PMID 28938000, 2017). "We have reported that the presence of CAFs expressing PDPN is a predictor of a poor prognosis among patients with lung adenocarcinoma and squamous cell carcinoma of the lung, and PDPN itself has been shown to exert tumor-promoting effects using in vitro and in vivo models." (PMID 25909164, 2015). "In a study on lung adenocarcinoma patients, PDPN + CAFs showed higher expression of TGFB1 and were associated with CD204 + TAM infiltration in stage I lung squamous cell cancer (SqCC), suggesting that PDPN + CAFs were associated with an immunosuppressive tumour microenvironment." (PMID 36653841, 2023). "In addition, PDPN‐expressing CAFs are associated with a high number of CD204+ TAMs, and a low ratio of CD8+ T cells and FOX3+ T cells in immunohistochemical staining of lung adenocarcinoma specimens, suggesting that PDPN‐expressing CAFs help cancer cells escape host immunosurveillance." (PMID 35603909, 2022). "PDPN (+) CAF, the representative of immunosuppressive microenvironment of lung adenocarcinoma, can induce macrophage M2 polarization and inhibit immune-related lymphocytes, serving as a bridge between fiber microenvironment and immunosuppression." (PMID 36276279, 2022). "High PDPN expression in fibroblasts is significantly correlated with a poor prognosis in IDC of the breast, lung adenocarcinoma, and ovarian carcinoma." (PMID 24354864, 2013). "Although podoplanin (D2-40) is essentially not expressed in lung adenocarcinomas (3% of focally positive lung adenocarcinomas), it is positive in 60% of lung squamous cell carcinomas." (PMID 39941848, 2025). "However, PDPN-expressing CAFs enhance the progression of pancreatic invasive ductal carcinoma (IDC) and lung adenocarcinoma." (PMID 37993428, 2023). "Hoshino and colleagues found that podoplanin-expressing CAFs, but not normal human fibroblasts enhanced the tumor formation ability of human lung adenocarcinoma cells, an effect mediated by podoplanin activation of RhoA–ROCK signaling in CAFs." (PMID 30736372, 2019). "Previous studies showed that, Calretinin, Wilms tumor protein 1 (WT-1), HBME-1, D2-40 (podoplanin), Carcinoembryonic antigen (CEA), Napsin-A and Thyroid transcription factor 1 (TTF-1) are immunocytochemical indicators for distinguishing malignant mesothelioma from lung adenocarcinoma." (PMID 32731396, 2020). "On the other hand, human lung adenocarcinoma cells have been reported to not express PDPN." (PMID 32380790, 2020).
oral cancer (30 papers, 2010 to 2026). "High-standard methodological criteria were followed and only primary-level studies that strictly followed patients over time were analyzed, allowing causal relationships between podoplanin overexpression and oral cancer development to be established." (PMID 41228241, 2025). "Another interesting result was obtained for oral lichen planus, where podoplanin overexpression was significantly associated with a very increased risk of developing oral cancer (RR = 17.13, 95% CI = 1.71–171.4, p = 0.02)." (PMID 41228241, 2025). "Independently, our prior study showed that DDR1, COL4A5, COL4A6 and PDPN are statistically associated with angiolymphatic invasion in matched tumor-adjacent normal tissues from 40 Taiwanese oral cancer patients." (PMID 34869001, 2021). "On the other hand, it was reported that co-expression of the CSC marker ALDH1 and podoplanin in pre-neoplastic oral leukoplakia is associated with a high risk of developing oral cancer." (PMID 30736372, 2019). "The relationship of podoplanin in tumor invasion and its expression in human cancers indicate that it can be used as a biomarker for malignant transformation risk assessment and tumor progression biomarker for oral cancer." (PMID 26558136, 2015). "Recently, podoplanin has been shown to be a candidate marker for cancer stem cells, which is associated with cancer cell invasion and migration, as well as prognosis, in a number of types of cancer, including esophageal squamous cell carcinoma, lung squamous cell carcinoma and oral cancer." (PMID 26095281, 2015). "In oral leukoplakia, high podoplanin expression has been associated with an increased risk of progression to invasive cancer, suggesting that podoplanin could serve as a powerful biomarker to predict the risk for oral cancer development in patients with oral leukoplakia." (PMID 20196862, 2010). "Neutralising antibodies targeting PDPN showed inhibition of tumour growth and metastasis in xenograft models for osteosarcoma, oral cancer, and malignant pleural mesothelioma (MPM), supporting clinical assessment of anti-PDPN antibodies in the future." (PMID 39780187, 2025). "For example, PDPN has emerged as a functionally relevant biomarker and potential chemotherapeutic target to prevent and treat oral cancer." (PMID 35177067, 2022). "Depth of invasion (DOI) was measured for nineteen cases of oral cancers, and it was observed that podoplanin reactivity was higher in tumors with DOI greater than or equal to five millimeters than in tumors with a depth of invasion less than five millimeters." (PMID 36247509, 2022). "In oral cancer, malignant p-EMT cells located at the invasion front are in proximity to CAFs (FAP+PDPN+) and are statistically associated with nodal metastasis and perineural invasion." (PMID 34869001, 2021). "We previously established CasMab against podoplanin (PDPN), which is expressed in many cancers, including oral cancers." (PMID 33000243, 2020). "We previously established CasMab against PDPN, which is expressed in many cancers, including oral cancers." (PMID 32923698, 2020). "Note that the PDPN staining is reminiscent of poor prognosis markers previously documented in oral cancer and premalignant lesions." (PMID 32244515, 2020). "Expression of podoplanin is rarely seen in normal oral mucosa, but is frequently seen in oral cancers." (PMID 31508790, 2019). "As this was the first study about the joint expression of podoplanin and moesin in oral cancer, further investigations based on in vitro assays are necessary for better evaluation of the participation of these molecules together in the tumor invasion process." (PMID 29310601, 2018). "PDPN promotes OSCC cell motility to drive tumor invasion and metastasis that cause most oral cancer deaths." (PMID 25826087, 2015). "Taken together, reports indicate that PDPN expression is notably increased in over 30% of pre-malignant oral lesions and in over 60% of oral cancers." (PMID 25826087, 2015).
oral cancer (continued). "Supporting this notion, podoplanin has been identified as a marker of malignant transformation and poor prognosis in oral cancer." (PMID 20196862, 2010). "In some studies, podoplanin was observed to be expressed in some hyperplastic and dysplastic lesions adjacent to primary oral cancers, suggesting that podoplanin expression may occur in early oral tumors and may play a role in malignant transformation." (PMID 36077194, 2022). "In xenograft models with HSC-2 cells, a mouse-human chimeric mAb, chLpMab-23, exerted antitumor activity using human natural killer cells, indicating that chLpMab-23 may be useful for antibody therapy against PDPN-expressing oral cancers." (PMID 33000243, 2020). "In xenograft models with HSC-2 cells, a mouse-human chimeric mAb, chLpMab-23, exerted antitumor activity using human natural killer cells, indicating that chLpMab-23 may be advantageous for antibody therapy against PDPN-expressing oral cancers." (PMID 32923698, 2020). "PDPN has emerged as a clear target for oral cancers and precancerous lesions." (PMID 25826087, 2015). "Recent studies have demonstrated that podoplanin was expressed in some hyperplastic and dysplastic lesions adjacent to the primary oral cancers, suggesting that expression of podoplanin may occur in early oral tumorigenesis and may play a role in the malignant transformation." (PMID 26558136, 2015). "The oncogenic properties of podoplanin were confirmed in human oral SCC cell lines expressing endogenous podoplanin, as its knockdown significantly reduced the tumorigenic capacities of HN2 and HN5 oral carcinoma cells." (PMID 30736372, 2019). "Indeed, PDPN may serve as a chemotherapeutic target for primary and metastatic cancer cells, particularly oral squamous cell carcinoma (OSCC) cells that cause most oral cancers." (PMID 25826087, 2015).
pancreatic cancer (27 papers, 2013 to 2025). "Recently, the PDPN expression in CAFs has been associated with poor prognosis for lung and pancreatic cancers." (PMID 33143259, 2020). "PDPN expression in stromal fibroblasts in pancreatic cancer was reported to be associated with lymphatic invasion, vascular invasion, the tumor size, histological grade, UICC classification T stage, and a shorter survival period." (PMID 28702871, 2018). "While high PDPN expression was predominantly found in lymphatic endothelium and often utilised as a marker for lymphatic vessels, elevated PDPN expression has been reported in CAFs and associated with poor outcomes in various cancer types, including lung, breast, and pancreatic cancers." (PMID 39780187, 2025). "PDPN-positive CAFs in pancreatic cancer are reportedly associated with a poor prognosis." (PMID 35625516, 2022). "CAFs and pancreatic cancer cell lines have also been shown to express PDPN (podoplanin), a protein known to induce platelet activation and aggregation through the CLEC‐2 (C‐type lectin receptor 2)." (PMID 40970582, 2025). "Following extensive characterisation, podoplanin has been identified as an efficient pan-marker of CAFs at the primary pancreatic tumour site, but labels only a minor population of hepatic MAFs12,13,15,18." (PMID 38678021, 2024). "Given the resemblance of myMAFs and iMAFs to previously defined CAF populations, we compared our annotated MAF clusters to the expression signatures of podoplanin+ myCAF and iCAF populations, derived from pancreatic tumours of KPC mice." (PMID 38678021, 2024). "In another study, PDPN expression in CAFs correlated with shorter overall survival of pancreatic cancer patients and a study suggests heterogeneity within the PDPN-positive stroma." (PMID 33333727, 2020). "A recent study identified a leucine-rich repeat containing 15 (LRRC15)-positive CAF subpopulation within the PDPN-positive CAF population in pancreatic cancer mouse model (Pdx1-Cre; lox-stop-lox-KrasG12D/+; p16/p19lox/lox)." (PMID 33333727, 2020). "In the present study, PDPN-expressing stromal cells in pancreatic cancer also expressed α-SMA, suggesting that they were most likely derived from PSCs." (PMID 28702871, 2018). "We performed immunohistochemical staining for D2-40 and α-SMA to evaluate PDPN expression in pancreatic cancer." (PMID 28702871, 2018). "Since pancreatic cancer is rich in fibrous tissues, we investigated the correlation between PDPN expression in stromal fibroblasts in invasive ductal carcinoma of the pancreas (IDCP) and prognosis in humans." (PMID 28702871, 2018). "Further investigations are needed to realize useful targeting therapy against PDPN in pancreatic cancer." (PMID 28702871, 2018). "Although this antibody is promising for molecular targeting therapy against PDPN-expressing cancers, PDPN is expressed only on the stromal fibroblasts surrounding tumors in pancreatic cancer." (PMID 28702871, 2018). "The areas that expressed PDPN in the pancreatic cancer also expressed α-SMA, a marker of stromal fibroblasts." (PMID 28702871, 2018). "For example, using the transwell co-culture system, it was found that migratory and invasive properties of pancreatic cancer cells were much higher when they were co-cultured with stromal fibroblasts highly expressing podoplanin." (PMID 28938000, 2017). "When pancreatic cancer cells were co-cultured with fibroblasts having high podoplanin expression, their motility and invasiveness were increased in comparison to CAFs with low expression of the PDPN." (PMID 28938000, 2017). "We sorted CAFs according to PDPN expression, and analyzed the functional differences between PDPN+ CAFs and PDPN– CAFs using indirect co-culture with pancreatic cancer cell lines." (PMID 24354864, 2013). "PANC-1, SUIT-2, and KP2 pancreatic cancer cells were co-cultured with CAF1 (high PDPN-expressing cells) or CAF2 (PDPN– cells) in the transwell system." (PMID 24354864, 2013).